IL6ST (interleukin 6 cytokine family signal transducer)
Diseases named in the same sentence as IL6ST in open-access papers (continued):
Sharing a sentence is not in itself a finding about the gene and the disease.
type 1 diabetes (3 papers, 2022 to 2025). "We found evidence for a shared causal variant between the risk of type 1 diabetes and whole-blood IL2RA (rs61839660, posterior probability 100%), IL6R (rs10908839, posterior probability 96.5%) and IL6ST gene expression (rs7731626, posterior probability 97.0%)." (PMID 39271518, 2024). "We did not observe such robust evidence for co-localisation between IL2RA, IL6R, IL6ST or TYK2 eQTL and the risk of type 1 diabetes in other cell types or in spleen or pancreas." (PMID 39271518, 2024). "To study which specific blood immune cells or tissues mediate the association between IL2RA, IL6R, IL6ST and TYK2 expression and type 1 diabetes risk, we analysed their pairwise co-localisation with type 1 diabetes risk in spleen, pancreas and subsets of blood immune cells." (PMID 39271518, 2024). "The OR (95% CI) of type 1 diabetes per 1-SD increase in the genetically proxied gene expression of IL2RA, IL6R and IL6ST were 0.22 (0.17, 0.27), 1.98 (1.48, 2.65) and 1.90 (1.45, 2.48), respectively." (PMID 39271518, 2024). "Interestingly, a recent integrative analysis of genetic association, functional genomics data and protein–protein networks identified DGKQ as a potential novel type 1 diabetes therapeutic gene target along with other novel and known targets, e.g., IL2RA, IL6ST, IL6R and TYK2." (PMID 35142878, 2022). "However, since IL6ST expression in CD4+ and CD8+ naive or central memory T cells co-localised with type 1 diabetes and IL6R expression did not, it is tempting to speculate that trans-signalling might be more important than classic IL-6 signalling in the pathogenesis of type 1 diabetes." (PMID 39271518, 2024).
Allergy (2 papers, 2024 to 2025). An allergy is an immune response or reaction to substances that are usually not harmful. "While the IUIS 2022 classification report states that allergy or atopy is characteristic for these conditions, it does not do so for ARPC1B, PLCG2, and IL6ST deficiencies – all of which had a high prevalence of allergy in our study." (PMID 41142799, 2025).
autosomal dominant HIES (2 papers, 2021 to 2023). "Like STAT3-associated HIES, IL6ST loss-of-function variant mosaicism is probably present in some patients with IL6ST autosomal dominant HIES." (PMID 38133879, 2023).
Duchenne muscular dystrophy (2 papers, 2021 to 2024). Duchenne muscular dystrophy (DMD) is a neuromuscular disease characterized by rapidly progressive muscle weakness and wasting due to degeneration of skeletal, smooth and cardiac muscle. "Treatment in the Duchenne muscular dystrophy mouse model with these IL6ST decoy receptor EVs resulted in a reduced phosphorylation of STAT3 in muscles; further functional studies verified the in vivo activity of the decoy receptor EVs as a potential therapy." (PMID 33579329, 2021). "In studies using muscle cells and a mouse model of Duchenne muscular dystrophy (DMD), IL6ST DR EVs successfully inhibited the activation of STAT3, a protein involved in inflammation and muscle degeneration." (PMID 39184952, 2024).
endometrial cancer (2 papers, 2018 to 2022). Primary or metastatic malignant neoplasm involving the endometrium (mucous membrane that lines the endometrial cavity). "Taken together, Efp is suggested to promote endometrial cancer by enhancing the signals of NF-κB and its related factors IL6ST and IL18 in addition to downregulation of 14-3-3σ protein, an Efp ubiquitin ligase-substrate." (PMID 30586414, 2018). "Intriguingly, Efp knockdown represses NF-κB-dependent transactivation and transcription of target genes, such as IL6ST and IL18, in endometrial cancer cells." (PMID 30586414, 2018).
hepatocellular adenoma (2 papers, 2022 to 2023). A benign epithelial neoplasm arising from the hepatocytes. "IL6ST is recognized as an oncogene involved in tumorigenesis and associated with inflammatory hepatocellular adenomas." (PMID 35402515, 2022). "To identify the spectrum of constitutively active IL6ST gain-of-function variants, we performed a meta-analysis of four independent cohorts that investigated hepatocellular adenoma and COSMIC database entries that investigated liver tumors, specifically HCA." (PMID 38133879, 2023).
lung adenocarcinoma (2 papers, 2020 to 2021). A carcinoma that arises from the lung and is characterized by the presence of malignant glandular epithelial cells. "Furthermore, IL6ST was positively related to survival in head and neck cancer, kidney clear cell carcinoma, and lung adenocarcinoma." (PMID 34576335, 2021).
mental disorder (2 papers, 2020 to 2024). A disease that has its basis in the disruption of mental process. "A number of studies demonstrate that impaired CNTF signaling caused by mutations in the genes of the receptor complex CNTFR*gp130 (CNTFR and IL6ST genes, respectively) may contribute to mental disorders." (PMID 38646100, 2024).
preeclampsia (2 papers, 2021 to 2024). Preeclampsia is a hypertensive disorder of pregnancy that is characterized by new-onset hypertension with proteinuria presenting after 20 weeks of gestation, and depending on mild or severe forms may initially present with severe headache, visual disturbances, and hyperreflexia. "Several hub genes, including ELMO1, YWHAE, and IL6ST, were significantly reduced in the placental vessels in preeclampsia." (PMID 39600942, 2024).
schizophrenia (2 papers, 2021 to 2024). A major psychotic disorder characterized by abnormalities in the perception or expression of reality. "We found diagnostic increases in SERPINA3, TNFα, IL1β, IL6, and IL6ST transcripts in schizophrenia compared with controls (p < 0.02–0.001)." (PMID 31168068, 2021). "A modest but statistically significant (F = 6.114, df = 1,53, p = 0.017) increase was found for IL6ST mRNA in people with schizophrenia compared with controls, whereas IL8 and IL18 mRNAs (both F < 1.0, df = 1,52/53, p > 0.05) were unchanged." (PMID 31168068, 2021). "Of the markers that did not contribute to the final cluster, IL8 and IL18 mRNAs were not significantly different between the subgroups, whereas IL6ST was increased in both the schizophrenia/high and schizophrenia/low immune subgroups compared with the control/low immune subgroup." (PMID 31168068, 2021).
ZIKV infection (2 papers, 2020 to 2024). "Interestingly, miR-142-5p was significantly downregulated upon ZIKV infection, whereas cellular targets of miR-142-5p, IL6ST and ITGAV, were upregulated." (PMID 32902370, 2020). "We also analysed the potential role of putative miR-142-5p target genes, IL6ST and ITGAV, during ZIKV infection." (PMID 32902370, 2020).
adenoma (1 paper, 2024). A neoplasm arising from the epithelium. "In patient samples, adenoma patients exhibited increased expression of genes associated with the tumor immune microenvironment, such as IL6ST, collagen family members, and CRC transition markers, such as GLI3 and PIEZO2, in CARD11+ adenoma patients." (PMID 39408697, 2024). "For the validation of some key genes identified in adenoma (IL6ST, GLI3) and carcinoma (MAPK8IP2, CPEB4) patients, survival analysis was completed by using the Kaplan–Meier Plotter." (PMID 39408697, 2024).
age-related macular degeneration (1 paper, 2016). Age-related loss of vision in the central portion of the retina (macula), secondary to retinal degeneration. "Knockout of IL6ST increases photoreceptor cell death not only in a light-induced retinal damage model but also in other photoreceptor degeneration models such as retinitis pigmentosa and age-related macular degeneration." (PMID 27242532, 2016).
alcohol abuse (1 paper, 2024). The use of alcoholic beverages to excess, either on individual occasions ("binge drinking") or as a regular practice.
aneurysm (1 paper, 2025). Bulging or ballooning in an area of an artery secondary to arterial wall weakening. "Regarding genetic factors associated with aneurysm development, interleukin 6 cytokine family signal transducer (IL6ST) emerges as a critical player in vascular smooth muscle cell (VSMC) phenotypic transition." (PMID 41204371, 2025).
atopic dermatitis (1 paper, 2025). "Selective loss-of-function variants in IL6ST are associated with hyper-IgE syndrome, leading to distinct impairments in T cell phenotype and function and recessive forms of hyper-IgE syndrome with eosinophilia and atopic dermatitis." (PMID 39859044, 2025). "Altered IL6ST signaling can exacerbate inflammatory skin conditions, such as atopic dermatitis." (PMID 39859044, 2025).
breast invasive carcinoma (1 paper, 2024). "IL6ST gene expression was positively correlated with such infiltration in breast invasive carcinoma-Basal with a similar significance." (PMID 39201290, 2024).
Burkitt lymphoma (1 paper, 2014). A rare form of malignant mature B-cell non-Hodgkin lymphoma. "In particular, we analyzed the IL-6 receptor genes (IL-6Rα and IL-6ST), PTEN and WT1 expression for their possible relevance to Burkitt lymphoma." (PMID 24731550, 2014).
cholangitis (1 paper, 2024). An acute or chronic inflammatory process affecting the biliary tract. "Additionally, JAK1 was associated with essential tremor (333.1, P = 1.03 × 10−2) and RB1CC1 displayed an association with cholangitis (575.1, P = 1.02 × 10−2) and IL6ST with noninfectious gastroenteritis in UK Biobank (558, P = 3.14 × 10−2)." (PMID 38741190, 2024).
Chronic colitis (1 paper, 2016). A chronic inflammatory disease of the large intestine (colon, cecum and rectum). "The IL6ST/gp 130 is known to regulate transduction of proinflammatory cytokines, i.e., IL-6 and IL-27, which their increased production has been reported in CD patients with chronic colitis." (PMID 27065983, 2016).
colon adenocarcinoma (1 paper, 2024). "R was used to analyze interleukin 6 cytokine family signal transducer (IL6ST) expression in The Cancer Genome Atlas Colon Adenocarcinoma database." (PMID 39344518, 2024).
colorectal adenoma (1 paper, 2024). An adenoma that arises from the colon or rectum. "Genes related to CARD11 overexpression in colorectal adenoma patients included IL6ST, GLI3, and PIEZO2, as well as the collagen-related gene family, whilst MAPK8IP2 gene expression was dramatically elevated in CARD11+ carcinoma patients." (PMID 39408697, 2024).
diabetic cardiomyopathy (1 paper, 2014). Diabetic cardiomyopathy is a disorder of the heart muscle in people with diabetes. "Our molecular analysis showed increased levels of Cxadr, Il6st, Pdgfra, and Slc2a1 in the LV of both Wt and Hif1a+/- diabetic hearts which corresponds to the onset of pathological processes associated with cardiac remodeling in diabetic cardiomyopathy." (PMID 24502509, 2014).
dyslipidaemia (1 paper, 2018). "IL-6 and interleukin 6 signal transducer (IL6ST) have been identified as dyslipidaemia susceptibility loci." (PMID 30157878, 2018).
Fibroadenoma (1 paper, 2024). A benign tumor of the breast characterized by the presence of stromal and epithelial elements. "In contrast, fibroadenomas had elevated expression of Il6st, Lifr, Tgfβr2, and transcription factor Zeb2." (PMID 38334641, 2024).
glioblastoma (1 paper, 2023). The most malignant astrocytic tumor (WHO grade IV). "Interestingly, a study showed that local anesthetics could attenuate glioblastoma stem cell proliferation and self‐renewal via diminishing ZDHHC15‐mediated palmitoylation of interleukin 6 signal transducer (IL6ST, also named GP130)." (PMID 36018061, 2023).
glycogen storage disease (1 paper, 2015). "Of note, H-HCA do not occur in patients with glycogen storage disease (GSD), neither are they associated with CTNNB1, IL6ST, GNAS, and STAT3 mutations." (PMID 26404250, 2015).
HIES syndrome (1 paper, 2023). "Heterozygous, dominant negative mutations in IL6ST (DN-IL6ST) can also cause AD-HIES syndrome." (PMID 36986378, 2023).
liver cancer (1 paper, 2023). An epithelial or non-epithelial malignant neoplasm that arises from the liver. "Impaired degradation of the transcriptional coactivator YAP1 and IL6ST (interleukin 6 cytokine family signal transducer), two proteins deregulated in liver cancer, has been shown to promote tumor growth." (PMID 35435804, 2023).
lymph node metastasis (1 paper, 2021). "IL6ST correlates with LVI in samples without lymph node metastasis and perineural invasion." (PMID 34210062, 2021).
meningioma (1 paper, 2026). A generally slow growing tumor attached to the dura mater. "IL6R and IL6ST are predicted targets of hsa-miR-21-5p downregulated in atypical/anaplastic meningiomas." (PMID 42196381, 2026). "Hsa-miR-21-5p enhanced proliferation and viability of KT21-MG1 meningioma cells and showed a regulatory effect on IL6R, IL6ST and other predicted target genes TIMP3, PIK3R, RHOB, and SASH1 by interacting with 3'UTRs." (PMID 42196381, 2026).
metastatic tumors (1 paper, 2024). "Moreover, Z-GS also decreased the expression of FXR, IL-6, IL-6ST, and p-STAT3 (Tyr705) in FXR-overexpressed A549 metastatic tumors." (PMID 38360812, 2024).
nephritis (1 paper, 2014). Inflammation of renal tissue. "Fabp4, Gsn, Il6st, and Ly6e, were associated with nephritis and Col18a1, Prom1, and Scd1 with renal cell carcinoma." (PMID 25409434, 2014).
osteoporosis (1 paper, 2024). A condition of reduced bone mass, with decreased cortical thickness and a decrease in the number and size of the trabeculae of cancellous bone (but normal chemical composition), resulting in increased fracture incidence. "In addition, the specific IL6ST inhibitor bazedoxifene (BZA) has long been approved by the US FDA as a selective modulator of estrogen receptors to treat osteoporosis, suggesting the promise of IL6ST inhibitors as drugs." (PMID 39007267, 2024).
ovarian endometriosis (1 paper, 2025). A non-neoplastic disorder characterized by the growth of endometrial tissue in the ovaries. "Immunohistochemical analysis (IHC) revealed markedly elevated expression of IL6ST in endometrial tissue of patients with ovarian endometriosis." (PMID 39821173, 2025).
pancreatic cancer (1 paper, 2022). "LIF receptor and its co-receptor IL-6 signal transducer (IL6ST, gp130) interact with STAT3 in human pancreatic cancer cells stimulated with CAF-conditioned medium." (PMID 35159011, 2022).
Parkinsonism (1 paper, 2024). Characteristic neurologic anomaly resulting from degeneration of dopamine-generating cells in the substantia nigra, a region of the midbrain, characterized clinically by shaking, rigidity, slowness of movement and difficulty with walking and gait. "Two significant gene clusters (clusters 7 and 73) included genes previously associated with Parkinsonism (FIG4 and VAC14) and IBD (IFNAR1, IL6ST, ATG16L1, and NOD2)." (PMID 38741190, 2024).
Peri-Implantitis (1 paper, 2019). An inflammatory process with loss of supporting bone in the tissues surrounding functioning DENTAL IMPLANTS. "As expected, the presence of inflammatory cytokines and chemokines, particularly IL1B, IL6, its signal transducer IL6ST, and CXCL2, was clearly observed at the mRNA level in the peri-implantitis affected samples." (PMID 31242601, 2019).
polymyalgia rheumatica (1 paper, 2024). A syndrome characterized by pain, stiffness, and tenderness of the proximal muscle groups including the shoulder, pelvic girdle and the neck. "Overall, our approach was able to capture known associations with IL6-R related genes and identified an association between IL6ST and polymyalgia rheumatica." (PMID 39563277, 2024). "Finally, we show that this approach can be used to identify drug indication expansion opportunities using genes related to the IL6 receptor as a case study and identify an association between IL6ST and polymyalgia rheumatica." (PMID 39563277, 2024). "Finally, we applied this approach to genes related to the IL6 receptor and identified an association between IL6ST and polymyalgia rheumatica supporting the recent approval of Sarilumab for this indication." (PMID 39563277, 2024). "Finally, using this approach, we detected anassociation between the IL6 receptor signal transduction gene IL6ST and polymyalgia rheumatica, an indication for which sarilumab, a monoclonal antibody against IL-6, has been recently approved." (PMID 39563277, 2024).
prostate adenocarcinoma (1 paper, 2023). "On the other hand, when we compared Prostate Adenocarcinoma (TGCA, PanCancer Atlas) dataset to that of our list of DEGs, we found IL6ST and ZBTB20." (PMID 37218885, 2023).
sarcoidosis (1 paper, 2020). Sarcoidosis is a multisystemic disorder of unknown cause characterized by the formation of immune granulomas in involved organs. "Our previously conducted epigenetic studies in sarcoidosis identified IL6ST and STAB1 as part of a miRNA-derived gene signature for complicated sarcoidosis." (PMID 33276795, 2020). "In the current study, IL6ST was significantly dysregulated only in TB granulomas (FC − 1.42 and p 0.0008), while STAB1 gene was significantly downregulated in lymph nodes in sarcoidosis (FC − 1.64, p 0.0014)." (PMID 33276795, 2020).
uterine cancer (1 paper, 2021). Primary or metastatic malignant neoplasm involving the uterine corpus and/or the cervix. "Furthermore, bladder, cervical, endometrioid, and uterine cancers, displayed IL6 upregulation and both IL6R and IL6ST downregulation." (PMID 34576335, 2021).